MTOR (mechanistic target of rapamycin kinase)
Diseases named in the same sentence as MTOR in open-access papers (continued):
Sharing a sentence is not in itself a finding about the gene and the disease.
bladder cancer (continued). "The HDAC-inhibitor sodium butyrate has been shown to induce apoptosis in the bladder cancer cell lines, T24 and 5637, by increasing ROS production via activation of AMP-activated protein kinase (AMPK) and inactivation of the mechanistic target of rapamycin (mTOR) pathway." (PMID 34073079, 2021). "Furthermore, long non-coding RNA UCA1 is associated with mTOR-mediated glucose consumption and lactate production in 5637 human bladder carcinoma cells, although no direct interaction between mTOR and UCA1 was demonstrated." (PMID 33466735, 2021). "Concerted action on ROS and mTOR/Akt may, therefore, serve to combat both growth and invasive activity of bladder cancer, but pertinent clinical trials have not yet been presented." (PMID 34073079, 2021). "Recently, luteolin was reported to inhibit bladder cancer cell viability and induce G2/M cell cycle arrest via upregulation of p21/WAF1 and reduction of phosphorylated S6 (p-S6), a key downstream molecule in the mechanistic target of rapamycin (mTOR) signaling pathway." (PMID 33996570, 2021). "Thus, SPAG5 might regulate bladder cancer proliferation and progression via the downstream PI3K/AKT/mTOR signaling pathway." (PMID 34162370, 2021). "As indicated by recent studies, UCA1 activates mTOR by upregulating HK2 and increases glycolysis through both the activation of STAT3 and the repression of miR-143, thereby revealing a novel glucose metabolism regulatory pathway, UCA1-mTOR-STAT3/miR-143/HK2, in bladder cancer cells." (PMID 30134946, 2018). "Also our data indicate possible crosstalk between PI3K/Akt/mTOR and MAPK/ERK pathway, thus suggesting the potential of concomitant targeting of MAPK/ERK pathway to enhance antitumor effect of PI3K/mTOR dual inhibitors in cisplatin-resistant bladder cancer." (PMID 24969552, 2014). "In bladder cancer, 4EBP1 was shown to be regulated by PI3K but not through mTORC1, and mTOR-independent 4EBP1 phosphorylation has been associated with resistance to mTOR kinase inhibitors." (PMID 24131622, 2013). "Although Lkb1 was not previously linked with bladder cancer and very few Lkb1 mutations were found in human bladder cancer, this kinase is a known regulator of TSC1/2 complex via AMPK and subsequent suppression of mTOR." (PMID 21283818, 2011). "In addition, via inhibiting the mTOR signaling pathway by directly binding to the EIF3G protein, exogenous overexpression of LINC02446 could inhibit cellular proliferation, migration and invasion in bladder cancer." (PMID 34631703, 2021). "The protein network associated with the three main molecules is involved in the canonical signaling pathways of bladder cancer, PI3K/AKT, and mTOR." (PMID 35864526, 2022). "The expressions of FAK, non-phosphorylated and phosphorylated PI3K and non-phosphorylated and phosphorylated mTOR all decreased in T24 and RT4 bladder cancer cells with an increasing flaccidoxide-13-acetate concentration." (PMID 29280977, 2017). "The expression of p-AKT, p-mTOR, p-p70S6K and p-ERK1/ERK2 was consistently significantly increased, whereas AKT, mTOR, p70S6K and ERK1/ERK2 were not significantly different in human bladder cancer tissues and matched ANT." (PMID 26375441, 2015). "Thus, inhibition of mTOR/S6K1 activity may be an effective strategy for sensitizing cancer cells to apoptotic stimuli, and mTOR/S6K1-mediated downregulation of Mcl-1 is supposed to be responsible for the evodiamine-mediated enhancement of TRAIL-induced apoptosis in bladder cancer cells." (PMID 24566141, 2014). "Therefore, to simulate the downstream effects of loss of function mutations in MLL2 and to investigate their relationships with alterations of the mTOR pathway, we carried out MLL2 silencing with a specific short hairpin RNA in T24 human bladder cancer cells where the MTOR gene is not altered." (PMID 27095575, 2016).
bladder cancer (continued). "Thus simultaneous suppression of PI3K and mTOR without activation of Akt and its downstream target signaling also supports the potent antiproliferative and proapoptotic activities of NVP-BEZ235 and cisplatin combination treatment in cisplatin-resistant bladder cancer cells." (PMID 24969552, 2014).
cardiac hypertrophy (311 papers, 2007 to 2026). "Collectively, Class I HDACs are capable of modulating the Akt, MAPK and mTOR signalling pathways, as well as the expression of genes associated with hypertrophy, thereby contributing to the initiation and progression of cardiac hypertrophy." (PMID 40497340, 2025). "The regulation of autophagy by mTOR is most closely linked to heart disease, particularly in the context of myocardial hypertrophy and ischemia–reperfusion injury." (PMID 40002810, 2025). "Attenuation of BCAA-induced mTOR activity by treatment with rapamycin prevented cardiac hypertrophy and restored a normal phenotype in mitolnc-deficient animals." (PMID 38567728, 2024). "In mammals, the activation of mTOR signalling is associated with the development of cardiac hypertrophy." (PMID 35588119, 2022). "Further to PAH, it was found that, in animals with cardiac hypertrophy and cardiac failure (caused by transverse narrowing of the aorta), rapamycin weakens cardiac dysfunction and remodeling by suppressing mTOR." (PMID 35163076, 2022). "The function of mTOR signaling in hypoxia is of continued significance because mTOR is implicated in cardiac hypertrophy in which hypoxia and oxidative stress predominate." (PMID 36133808, 2022). "The PI3K/Akt pathway is involved in cardiac remodeling, especially hypertrophic cardiomyopathy, via the mTOR pathway, and empagliflozin can suppress the cardiac hypertrophy caused by the PI3K/Akt/mTOR pathway." (PMID 36337862, 2022). "Mechanistically, lack of MKK6 blunts p38α activation while causing MKK3-p38γ/δ hyperphosphorylation and increased mammalian target of rapamycin (mTOR) signaling, resulting in cardiac hypertrophy." (PMID 35971771, 2022). "Berberine alleviates pressure overload-induced cardiac hypertrophy and dysfunction through the inhibition of mTOR and p38 MAPK signaling pathways associated with enhanced autophagy." (PMID 34007292, 2021). "Studies have shown that related genes can inhibit cardiac hypertrophy caused by pressure overload by inhibiting the AKT/mTOR pathway to promote autophagy." (PMID 33778070, 2021). "The mammalian target of rapamycin (mTOR) signaling cascade is implicated in the induction of cardiac hypertrophy and fibrosis." (PMID 31994601, 2020). "Deletion of PTEN reportedly causes cardiac hypertrophy in mice through the activation of mTOR signaling and inhibition of autophagy." (PMID 32595507, 2020). "mTOR can be activated by pathological stimulation to cause cardiac hypertrophy, although it can be partially suppressed by rapamycin." (PMID 32863202, 2020). "In the present study, we used this system to establish the link between mTOR signalling and cardiac hypertrophy under SIRT6 deficient conditions." (PMID 31372634, 2019). "Collectively these results indicate that hyperactive mTOR signalling contributes to increased protein synthesis and cardiac hypertrophy in SIRT6 deficient mice." (PMID 31372634, 2019). "Because PTEN is a negative regulator of the autophagic PI3K/AKT/mTOR cascade, it has been concluded that miR-29-associated PTEN suppression activates the PI3K/AKT/mTOR system, thereby abrogating autophagy and promoting cardiac hypertrophy." (PMID 31547607, 2019). "These authors suggested an inhibition of AMP-activated protein kinase (AMPK), which behaves as a negative regulator of cardiac hypertrophy, activating the mTOR/p70S6K pathway, which increases protein synthesis associated with cardiac hypertrophy." (PMID 31771303, 2019). "A number of studies have demonstrated that the Akt/mTOR signaling cascade is associated with cardiac hypertrophy." (PMID 31149027, 2019).
cardiac hypertrophy (continued). "mAb A treatment limited cardiac hypertrophy, an effect which was associated with abrogating mTOR/P70S6K signalling." (PMID 30626440, 2019). "Inhibition of AKT/mTOR signaling also attenuates or reverses pressure overload-associated cardiac hypertrophy, supporting our findings that there is a potential regulatory role for AKT/mTOR in pathological HCM in NSML." (PMID 28582432, 2017). "Increased phosphorylation of the Ser2448 residue of mTOR (mechanistic target for rapamycin) that results in activation of mTOR is a hallmark of cardiac hypertrophy." (PMID 29259233, 2017). "In the heart, increased BCAA levels can activate mTOR signaling, which is directly implicated in cardiac hypertrophy through protein synthesis regulation." (PMID 28692647, 2017). "To address the molecular basis of the restored cardiac dimensions of splice-rescue mice, we analyzed the expression of several proteins previously linked to cardiac hypertrophy signaling such as Erk1/2, Akt, mTOR, NFATc1, and JNK." (PMID 27889803, 2016). "To unravel the effect of MI14 on the signaling pathways involved in the development of cardiac hypertrophy, we examined phosphorylation levels of the hypertrophy-associated kinases mTOR, ERK, PKD, the MEF2 adaptor HDAC5 and the Ca2+ dynamics regulator phospholamban (PLN)." (PMID 41596248, 2026). "Therefore, it is possible that the inhibition of mTOR signaling during cardiac hypertrophy is due to the decreased conversion of DAG to PA caused by DGKζ deletion." (PMID 38250603, 2024). "Therefore, mitochondrial ROS generation is implicated in insulin resistance and cardiac hypertrophy via mTOR-dependent mechanisms in diabetic conditions." (PMID 36670985, 2023). "In addition to the TLR4 pathway, the PI3K/Akt/mTOR signaling pathway has also been shown to play a role in cardiac hypertrophy caused by pressure overload and blocking it almost diminished hypertrophy." (PMID 38140398, 2023). "Blockade of mTOR has been linked to cardiac protection and a reduction in cardiac hypertrophy." (PMID 37107252, 2023). "In addition, PTPN11 mutation has also been demonstrated to be harmful to myocardial hypertrophy and cardiac fibrotic remodeling through crosstalking with NF-κB pathway and mTOR signaling." (PMID 36212153, 2022). "To investigate whether inhibition of mTOR caused reduced cardiac hypertrophy in Y-Sesn2 KO mice, we treated young WT mice and Y-Sesn2 KO mice with rapamycin or vehicle at the time of TAC or sham surgery." (PMID 32863202, 2020). "Thus, inactivation of mTOR is an important protective mechanism underlying the involvement of ALS in the pathological process of cardiac hypertrophy." (PMID 31994601, 2020). "Previously, it was reported that inhibition of mTOR by rapamycin attenuates pathological hypertrophic response by downregulating NF-κB signaling, whereas rapamycin has an additional improvement for cardiac hypertrophy in TLR4 deficient mice." (PMID 33324685, 2020). "Since SIRT6 deficiency leads to enhanced protein synthesis by virtue of increased activation of mTOR signalling, we tested whether pharmacological inhibition of mTOR signalling can rescue cardiac hypertrophy observed under SIRT6 deficient conditions." (PMID 31372634, 2019). "Rapamycin inhibition of mTOR activity can reverse cardiac hypertrophy in PTPN11-mutated LS mice." (PMID 31722741, 2019). "Animal studies suggested that blocking the activation of the mammalian target of rapamycin (mTOR) pathway might be effective to treat cardiac hypertrophy in LEOPARD syndrome (LS) caused by PTPN11 mutations." (PMID 31722741, 2019). "Moreover, the protein kinase B, Akt, or mTOR among other downstream regulators have also been implicated in cardiac hypertrophy." (PMID 29984246, 2018). "Inhibition of mTOR signaling may be closely related to the pathogenesis of cardiac hypertrophy, which may cause heart failure, and lead to morbidity and mortality." (PMID 30405071, 2018).
cardiac hypertrophy (continued). "Hence, given the central role of Akt–mTOR signaling in swimming-induced cardiac hypertrophy, we investigated the impact of moderate-intensity treadmill exercise on mTOR signaling and its associated impact on the structure and function of the murine heart." (PMID 25991723, 2015). "Indeed, hypertensive heart disease and hypertrophy are good examples of aging-associated hyperfunction also dependent on mTOR pathway." (PMID 24799459, 2014). "Additionally, increased O‐GlcNAcylation activates the mTOR signaling pathway, which is known to be closely associated with cardiomyocyte growth and hypertrophy, thereby further aggravating pathological cardiac hypertrophy and HF." (PMID 41394960, 2025). "However, the study for the underline mechanism of EGCG associated with AKT/mTOR signalling in cardiac hypertrophy and fibrosis is still unknown." (PMID 34607503, 2021). "Berberine could attenuate cardiac hypertrophy associated with enhanced autophagy via inhibiting activation the mechanism of the mammalian target of rapamycin (mTOR), extracellular signal-regulated kinase (ERK1/2), and p38 mitogen-activated protein kinase (MAPK) phosphorylation." (PMID 33101051, 2020). "Moreover, patients with gain-of-function mutations of PTPN11 and attenuated mTOR pathway may also have cardiac hypertrophy, which cannot be explained by the animal studies." (PMID 31722741, 2019). "This is because Class I HDAC inhibits the expression of tuberous sclerosis complex 2 (TSC2), which activates mTOR and contributes to the development of cardiac hypertrophy." (PMID 40497340, 2025). "It has been established that the majority of microRNAs, such as miR-19, -208, -99, -100, and, -181, are associated with cardiac hypertrophy and apoptosis, primarily through the MAPK and the PI3K/Akt/mTOR signaling pathways." (PMID 40463932, 2025). "mTOR and Gsk‐3β, as downstream molecules of Akt, are involved in mediating pathological cardiac hypertrophy." (PMID 40753540, 2025). "In the cardiovascular system, excessively high O‐GlcNAcylation can promote HF by activating the mTOR pathway or induce ventricular cardiomyocyte hypertrophy through PKA pathway activation, significantly exacerbating cardiovascular pathology." (PMID 41394960, 2025). "Taken together, these data suggest that QRICH1 exacerbates stress-induced pathological cardiac hypertrophy, potentially through the activation of the mTOR signaling pathway and its interaction with ATF6." (PMID 40355839, 2025). "Previous studies have pointed out that protein synthesis mediated by mTOR/4EBPs pathway plays an important role in cardiac hypertrophy." (PMID 41195005, 2025). "In conclusion, we demonstrate that MARCH5 promotes cardiac hypertrophy through the Akt/mTOR/Gsk‐3β/GATA4 pathway." (PMID 40753540, 2025). "The mTOR signaling pathway and its related components play a central role in cardiac hypertrophy, ischemia, autophagy, and cardiomyopathy, which reflects potential therapeutic targets." (PMID 40002810, 2025). "Previous studies have demonstrated that the PI3K/Akt/mTOR signaling pathway plays a crucial role in regulating cardiac hypertrophy." (PMID 41567385, 2025). "It appears from this that activation of PI3K/AKT/mTOR is essential for the development of cardiac hypertrophy." (PMID 40463932, 2025). "Given its involvement in cardiac hypertrophy, ischemia, autophagy, and cardiomyopathy, mTOR represents a critical target for potential therapeutic interventions aimed at treating or preventing heart disease." (PMID 40002810, 2025).
cardiac hypertrophy (continued). "The subsequent activation of CITED4 leads to the phosphorylation of mTOR, a key regulator of cell growth, thereby promoting exercise-induced cardiomyocyte proliferation and cardiac hypertrophy." (PMID 40136658, 2025). "miR-100-5p, known for its role in stress adaptation via mTOR suppression, promotes autophagy to mitigate oxidative and endoplasmic reticulum (ER) stress, as observed in cardiac hypertrophy." (PMID 41329722, 2025). "Conversely, administration of a PI3K inhibitor alleviates the degree of myocardial hypertrophy by suppressing the mTOR signaling pathway." (PMID 40797392, 2025). "The overexpression of miR-29a inhibits PTEN expression, activates the Akt/mTOR signaling pathway, suppresses autophagy, and ultimately leads to cardiac hypertrophy." (PMID 40002810, 2025). "For example, inhibition of the mTOR pathway, which has been shown to extend the lifespan and reduce cell senescence phenotypes in aged mice, is able to reduce cardiac hypertrophy and improve cardiac function in aging mouse models." (PMID 40305307, 2025). "In response to ISO, in QRICH1 KD mice, overexpression of ATF6 reactivated the mTOR signaling pathway, resulting in exacerbated cardiac hypertrophy and dysfunction." (PMID 40355839, 2025). "AMPK serves as an energy sensor and has been shown to inhibit cardiac hypertrophy by negatively regulating mTOR-signaling-mediated protein synthesis." (PMID 40104444, 2025). "While our study delineates the central role of the AMPK/SIRT1 axis, our KEGG enrichment analysis also suggests the potential involvement of other downstream pathways such as mTOR signaling and autophagy—key regulators of cardiac hypertrophy." (PMID 41010549, 2025). "As expected, the protective effect of 4-HCH against cardiac hypertrophy by reducing the activation of p-mTOR and p-MAPK (ERK1/2)." (PMID 39715792, 2025). "Activation of the mTOR pathway has been shown to ameliorate pathological cardiac hypertrophy by improving protein turnover and mitochondrial function." (PMID 41195005, 2025). "mTOR plays an essential role in exercise-induced cardiac hypertrophy, as it becomes highly phosphorylated in the myocardium following moderate endurance exercise." (PMID 40136658, 2025). "In diabetic cardiomyopathy, upregulation of the mammalian target of rapamycin (mTOR) pathway accelerates pyroptosis, resulting in myocardial hypertrophy and collagen deposition, which further exacerbate cardiac dysfunction." (PMID 39994107, 2025). "Our study identifies MARCH5 as a novel regulatory component in myocardial hypertrophy through its modulation of the Akt/mTOR/Gsk‐3β/GATA4 signalling axis." (PMID 40753540, 2025). "The increased expression of MYL3 promoted autophagy and exacerbated cardiac hypertrophy through the modulation of PI3K/Akt/mTOR and ERK signaling pathways." (PMID 40007621, 2025). "Previous research has shown inhibition of mTOR to have beneficial effects against cardiomyopathy, atherosclerosis, cardiac hypertrophy, and heart failure." (PMID 39086659, 2024). "Inactivation of mitolnc reduces activity of the BCKDH complex and results in accumulation of BCAAs in the adult heart, which enhances mTOR signaling and induces cardiac hypertrophy." (PMID 38567728, 2024). "On the other hand, mTOR inhibitors have been suggested to reduce cardiac hypertrophy by attenuating cardiac remodeling and reducing cardiac fibroblast proliferation and collagen secretion." (PMID 38792274, 2024). "The protein kinase B/mammalian target of rapamycin (Akt/mTOR) pathway is vital in mediating thyroid-induced heart hypertrophy." (PMID 38318568, 2024). "Inactivation of mitolnc in mice reduces BCKDH complex activity, resulting in accumulation of BCAAs in the heart and cardiac hypertrophy via enhanced mTOR signaling." (PMID 38567728, 2024).